MSR1 (macrophage scavenger receptor 1)
Description:
Membrane receptor that mediates the binding, endocytosis and phagocytosis of a broad range of ligands. Recognizes and internalizes modified forms of low-density lipoproteins including acetylated LDL (AcLDL) and oxidized LDL (OxLDL), thereby promoting cholesterol uptake and contributing to foam cell formation during atherogenesis. Binds various pathogen-associated and damage-associated molecules, including bacterial cell wall components, apoptotic cell debris and polyanionic ligands, supporting macrophage clearance activity in innate immune defense. Upon stimulation by CpG DNA, mediates activation of LYN, which phosphorylates SYK that is subsequently recruited to endosomal TLR9 to promote downstream TLR9 signaling. [Isoform III]: Does not internalize acetylated LDL.
Synonyms: CD204; SCARA1; SR-AI; SR-AII; SR-AIII; SR-A; SRA; phSR1; phSR2
Tractability: Antibody: its Gene Ontology location is reachable by antibodies, with high confidence; UniProt predicts a signal peptide or a membrane-spanning region. PROTAC: its protein half-life has been measured; a small molecule that binds it is known.
Target class: Membrane receptor
Gene: Protein-coding gene on chromosome 8 (16,107,878 to 16,567,490, reverse strand). Ensembl gene ENSG00000038945.
Subcellular location: Cell membrane
Pathways (Reactome):
Vesicle-mediated transport: Scavenging by Class A Receptors
Gene Ontology:
Molecular function: pattern recognition receptor activity; protein binding; amyloid-beta binding; cargo receptor activity; low-density lipoprotein particle binding; scavenger receptor activity
Biological process: positive regulation of toll-like receptor 9 signaling pathway; amyloid-beta clearance; cholesterol transport; negative regulation of gene expression; phagocytosis, engulfment; plasma lipoprotein particle clearance; positive regulation of cholesterol storage; positive regulation of macrophage derived foam cell differentiation; receptor-mediated endocytosis
Cellular component: plasma membrane; endocytic vesicle membrane; membrane
Genetic constraint (gnomAD): Loss-of-function variants: 51 observed, 47.14 expected, observed/expected ratio (o/e) 1.08, 90% interval 0.86 to 1.37. The synonymous counts are far from expectation, so gnomAD's model fits this gene poorly and the ratio says little. Missense variants: 732 observed, 533.78 expected, observed/expected ratio (o/e) 1.37, 90% interval 1.29 to 1.46. Synonymous variants: 225 observed, 180.98 expected, observed/expected ratio (o/e) 1.24, 90% interval 1.11 to 1.39.
Homologues: Orthologues: macaque MSR1 (95% identical), chimpanzee MSR1 (91% identical), dog MSR1 (81% identical), rabbit MSR1 (81% identical), pig MSR1 (77% identical), mouse Msr1 (71% identical), guinea pig MSR1 (67% identical), rat Msr1 (65% identical). Paralogues in human: SCARA5 (35% identical), MARCO (24% identical), COLEC12 (22% identical).
Diseases named in the same sentence as MSR1 in open-access papers:
MSR1 is named in the same sentence as 184 diseases in open-access papers, as found by Europe PMC text mining. Sharing a sentence is not in itself a finding about the gene and the disease. The quoted sentences say what the papers report.
glioma (46 papers, 2009 to 2025). A benign or malignant brain and spinal cord tumor that arises from glial cells (astrocytes, oligodendrocytes, ependymal cells). "MSR1, encoding the class A macrophage scavenger receptors, was reported to be influential in cancer progression and metastasis in vitro and in vivo and to be a marker of tumor-infiltrated macrophages within the tumor microenvironment in glioma." (PMID 36091778, 2022). "The identification of C5AR1 and MSR1 overexpression in the OT group may suggest differences in the NL vs OT glioma tumor-associated immune microenvironment." (PMID 33059718, 2020). "A previous study demonstrated that MSR1 inhibition suppressed migration, invasion, epithelial-mesenchymal transition, and proliferation in lower-grade glioma." (PMID 40438577, 2025). "We used siRNA to knockdown the expression of MSR1 and then evaluated the effect of MSR1 on the biofunctions of glioma cells, including migration, invasion, EMT, and proliferation." (PMID 36091778, 2022). "Cell migration and invasion abilities were dramatically decreased after MSR1 knockdown in glioma SHG44 and HS683 cells." (PMID 36091778, 2022). "Further characterization of these gene signatures indicated that the C5AR1 and MSR1 genes were significantly overexpressed in the OT cluster and, in general, in higher-grade gliomas." (PMID 33059718, 2020). "Using the first CGGA dataset, 14 samples were classified as NL gliomas with both SLC32A1/MSR1 and C5AR1/SYT5 gene signatures vs 263 OT samples." (PMID 33059718, 2020). "Overall, we envisage that the lower expression of C5AR1 in NL gliomas, by impacting negatively on MSR1-expressing M2 phenotype macrophages and positively on NK and CD4+/CD8+ T cells, favors anti-inflammatory and anti-tumoral cell signaling cascades." (PMID 33059718, 2020). "A machine learning-based approach identified C5AR1/SYT5 and MSR1/SLC32A1 signatures which were able to discriminate NL IDH-WT gliomas with high sensitivity and specificity in various glioma expression datasets." (PMID 33059718, 2020). "We have observed high HR (greater or equal to 0.5) for NLRC4, CASP1, NLRP12 and MSR1 genes in grade 3 & grade 4 glioma." (PMID 31186453, 2019). "On the other hand, the role of MSR1 in tumours has been elucidated, particularly in gliomas." (PMID 36515067, 2023). "It has been reported that high expression of MSR1 was an independent prognostic factor of glioma." (PMID 36515067, 2023). "In addition, MSR1 levels in TAMs are shown to have a positive correlation with the cancer’s grade in glioma and colorectal adenoma." (PMID 36325338, 2022). "MSR1 could also be a target for intensifying the current anti-glioma therapy." (PMID 36091778, 2022). "Each one of the two correlation coefficients manifested that both SPP1 and HMOX1 were consistently co‐expressed with 20 genes in glioma samples, such as VAMP8, RAC2, MSR1, CAPG and FBP1." (PMID 40495644, 2025). "We observed that significant upregulation of mRNA expression levels for three TAM markers, MSR1/CD204, CD86, and CD68, suggested that TGFB2 is pivotal in establishing a pro-tumorigenic TME in gliomas mediated through TAMs." (PMID 38539537, 2024). "The q-PCR results showed that MSR1 (p < 0.05), IL18 (p < 0.05), SLC11A1 (p < 0.05), and C3AR1 (p < 0.05) were highly expressed in the glioma tissue compared with the normal tissues." (PMID 37370848, 2023). "The numbers of CD163- and MSR1-positive cells were higher in the GBM slices than in grade II and grade III glioma specimens." (PMID 37391426, 2023). "Our in vitro experiments also confirmed that MSR1 was involved in the migration, invasion, EMT, and proliferation of glioma cells." (PMID 36091778, 2022). "We observed that the IRSs of PROS1, P2RY8, PLAU, CHI3L2, MSR1, CCR5, and TRIM38 were higher than its corresponding IRSs in low-grade glioma, while the IRSs of HAMP, CARD16, and S100A8 in high-grade glioma were lower than low-grade glioma." (PMID 34954691, 2021).
glioma (continued). "We identified two gene signatures composed of SLC32A1/MSR1 and SYT5/C5AR1 gene combinations whose expression alone strongly correlated with this subgroup of IDH-WT gliomas." (PMID 33059718, 2020).
atherosclerosis (31 papers, 2012 to 2025). A disease characterized by the build-up of fatty material and calcium deposition in the arterial wall resulting in partial or complete occlusion of the arterial lumen. "The significantly expressed and atherosclerosis-associated genes (MSR1, CD36, NR1H3) were detected by transcriptome analysis." (PMID 36613720, 2022). "Our group showed that deficiency of Sirt6 in bone marrow-derived cells increased atherosclerosis in ApoE knockout mice due to increased expression of scavenger receptor macrophage scavenger receptor 1 (MSR1) and foam cell formation." (PMID 34712151, 2021). "MSR1 encodes the scavenger receptor protein SR-A1 which has been shown to have a role in atherosclerosis by mediating uptake of modified LDL (primarily acetylated LDL); however, the underlying mechanisms are not yet fully elucidated." (PMID 31448116, 2019). "MSR1 has been documented to undergo changes in both physiological and pathological processes associated with macrophages, influencing conditions such as atherosclerosis and innate and adaptive immunity." (PMID 39776914, 2024). "In addition, Msr1 (macrophage scavenger receptor 1) has been implicated in many macrophage-associated physiological and pathological processes including atherosclerosis, Alzheimer's disease, and host defense." (PMID 35788904, 2023). "MSR1 is, as its name suggests, predominantly expressed in various macrophage cell types and is mainly altered in macrophage-associated physiological and pathological processes including atherosclerosis, Alzheimer’s disease, host defence, and cancer." (PMID 36325338, 2022). "MSR1, commonly known as a macrophage-specific gene, encodes the macrophage scavenger receptor 1, a trimeric integral membrane glycoprotein involved in various functional and disease-related mechanisms related to macrophages, including Alzheimer’s disease, atherosclerosis, and host defense." (PMID 39776914, 2024). "DDX5 then inhibits METTL3 methyltransferase activity, reducing m6A modifications and thus stabilizing MSR1 mRNA, increasing MSR1 expression, and inducing lipid uptake and atherosclerosis." (PMID 40066451, 2025). "MSR1 has been shown to have activity in macrophage polarisation, pro-inflammatory signalling, pathogen clearance, Alzheimer’s disease, atherosclerosis, non-alcoholic fatty liver disease, and cancer." (PMID 39510801, 2025). "The SARS-CoV-2 spike protein increases R-loop formation on MSR1 mRNA, leading to inhibition of macrophage lipid uptake and thereby alleviating atherosclerosis." (PMID 39850878, 2024). "Loss of SIRT6 in bone marrow-derived cells stimulates c-MYC transcription, thereby enhancing macrophage scavenger receptor 1 (Msr1) levels and increasing oxidized low-density lipoprotein to enhance foam cell formation and atherosclerosis." (PMID 39372420, 2024). "MSR1 participates in cell adherence, activation, and foam cell formation, processes involved in atherosclerosis development and progression." (PMID 36831031, 2023). "Nevertheless, several mechanisms pertaining to the activity and regulation of MSR1 in atherosclerosis have been elucidated in recent years." (PMID 36325338, 2022). "This highlights again that MSR1 can be attributed to both the pathophysiology of and protection against atherosclerosis." (PMID 36325338, 2022). "The function of MSR1 in the pathogenesis of atherosclerosis appears to be dependent on the mouse genetic background and apoE presence." (PMID 36325338, 2022). "The most extensively covered role of MSR1 is its activity in atherosclerosis, yet despite the abundance of investigations in this area there is ongoing debate regarding the true role of the receptor." (PMID 36325338, 2022). "It has also been described that macrophage NFATc3 acts to upregulate miR-204 which in turn depletes levels of MSR1 and protects against atherosclerosis by limiting lipid uptake and subsequent foam cell formation." (PMID 36325338, 2022).
atherosclerosis (continued). "Due to disparities in experimental results so far, the role that MSR1 plays in atherosclerosis is still controversial." (PMID 36325338, 2022). "Similar to Msr1, the expression of CD36 on macrophages has been linked to increased uptake of lipoproteins in atherosclerosis." (PMID 31429730, 2019). "Knockout of the scavenger receptors Cd36 and Msr1 resulted in reduced lipid uptake and lower intracellular lipid content in macrophages, as well as a relative suppression of macrophage proliferation in both established and early atherosclerosis." (PMID 40956333, 2025). "The third replicated protein, macrophage scavenger receptor types I and II (MSR1, also known as CD204), has been implicated in many macrophage-associated physiological and pathological processes, including atherosclerosis, Alzheimer’s disease, prostate cancer, and host defense." (PMID 36631443, 2023). "Contradictory findings of MSR1 activity in diseases such as atherosclerosis and sepsis may also potentially indicate a much more complex mechanism behind the activity of MSR1." (PMID 36325338, 2022). "Therefore, the first role described for MSR1 was in the pathogenesis of atherosclerosis, which kick-started further investigations into MSR1." (PMID 36325338, 2022). "MSR1 expression can also be induced by angiopoietin-like protein 8 (ANGPTL8), a hormone linked to the regulation of lipid metabolism and the development of atherosclerosis." (PMID 36325338, 2022). "Importantly in relation to atherosclerosis, genes related to lipid metabolism, which featured in resident macrophages, were downregulated (Plin2, Trem2, Lipa, Msr1, and Abcg1) by CLEC4A2 deletion." (PMID 35017526, 2022). "Perhaps a less obvious protective role played by MSR1 is the uptake of calciprotein particles and mineral debris from the blood circulation, this prevents soft tissue calcification and thus aids in the prevention of calcifying atherosclerosis." (PMID 36325338, 2022). "Additionally, Msr1 plays a major role in the development of cardiovascular diseases and atherosclerosis by increasing cellular lipoprotein internalization." (PMID 31429730, 2019). "In terms of atherosclerosis, there is controversy as to whether there are reduced lesions in apoE/Cd36/Msr1 triple knock-out mice, but there is consensus that absence of these receptors reduced lesion complexity and inflammation." (PMID 22470565, 2012). "Additional GWAS hits in the shared cross-species CAD/atherosclerosis subnetworks were peripheral nodes (e.g. CETP, PLCG2, BASP1, MSR1, ST5, ASAP2)." (PMID 38060277, 2023). "Genes MSR1, CCL2, and CXCL known to be involved in the development of atherosclerosis through the activation of LXR/RXR and PPARα were upregulated." (PMID 36831031, 2023). "Macrophage scavenger receptor 1 (MSR1) is responsible for the uptake of modified lipoprotein and is one of the key molecules in atherosclerosis." (PMID 36591228, 2022). "To date, MSR1 is known to be one of the major contributors to ox-LDL uptake, and its role in atherosclerosis has been extensively studied." (PMID 36591228, 2022). "In diseases such as IBD and atherosclerosis, writers can modulate the expression of solute carrier family 37 member 2 (SLC37A2), macrophage scavenger receptor 1 (MSR1), and scavenger receptor class B type 1 (SR-B1), inhibiting glycolysis and lipid uptake while promoting cholesterol efflux." (PMID 40066451, 2025). "Many of the genes differentially regulated during monocyte-to-macrophage differentiation (downregulated genes include JAK2, STAT6, TLR8, and TLR2, and upregulated genes include VEGFB, TGFB1, FN1, IL-1R2, SCARB1, MSR1, and CD163) have been previously reported in the pathogenesis of atherosclerosis." (PMID 25011540, 2014).
atherosclerosis (continued). "In line with this hypothesis, previous studies with MSR1 and CD36-knockout mice showed that disruption of each receptor pathway partially inhibited the uptake of modified LDL in macrophages and retarded atherosclerosis progression in a similar manner." (PMID 22470565, 2012). "Foamy macrophage generation and fibrosis was also impeded in mice lacking MSR1, indicating potential therapeutic benefit in non-alcoholic fatty liver disease (NAFLD) and other inflammatory diseases, such as atherosclerosis, where foam cells contribute to pathogenesis." (PMID 36325338, 2022).
prostate carcinoma (30 papers, 2003 to 2025). A carcinoma that arises from epithelial cells of the prostate gland. "Studies were performed to determine if macrophage scavenger receptor 1 (MSR1) mutations can be linked to hereditary prostate cancer." (PMID 37021836, 2023). "Association of MSR1 mutations with progression of prostate cancer and esophageal adenocarcinoma confirmed the involvement of this scavenger receptor to carcionogenesis." (PMID 36686729, 2022). "MSR1 is predominantly expressed by macrophages in both benign and cancerous prostate tissues, emphasizing the role of macrophage-derived mutated MSR1 in prostate cancer development." (PMID 36686729, 2022). "To date, three strong candidates are known, RNASEL at 1q25, ELAC2 at 17p11 and MSR1 at 8p22, each having been identified with germline mutations in prostate cancer families." (PMID 15714208, 2005). "This suggests that MSR1 mutations may only confer a moderate increase in prostate cancer risk, particularly in black men." (PMID 33076397, 2020). "Furthermore, several mutations in the MSR1 gene can be predictive of increased inheritable risk of developing prostate cancer linked to inflammation." (PMID 33076397, 2020). "However, there is controversy surrounding the association between MSR1 variants and prostate cancer risk." (PMID 33076397, 2020). "HLA-A in prostate cancer, MSR1 in familial prostate cancer, and EGFR in both castration-resistant prostate cancer and metastatic castration-resistant had the highest allele frequencies of splice-disrupt variations." (PMID 35286517, 2022). "The immunomodulatory effects of MSR1 were also confirmed during radiation therapy for prostate cancer." (PMID 36325338, 2022). "A high ratio of CD8+ T cells to MSR1+ TAMs indicated a favourable postoperative prognosis in prostate cancer." (PMID 36325338, 2022). "In situ vaccination with DCs in which MSR1 had been downregulated, alongside ionizing radiation, significantly suppressed the growth of murine prostate cancer and a reduction in distant metastases was also seen." (PMID 36325338, 2022). "Two SNPs in MSR1 (rs9325782, GEE p = 0.008 and rs2410373, FBAT p = 0.021) were associated with prostate cancer and three SNPs in ERBB4 (rs905883 GEE p = 0.0002, rs7564590 GEE p = 0.003, rs7558615 GEE p = 0.0078) were associated with breast cancer." (PMID 17903305, 2007). "Another hereditary prostate cancer gene candidate is MSR1 at 8p23 likewise involved in innate immune responses." (PMID 17280610, 2007). "Genes linked to prostate cancer susceptibility, including RNASEL, MSR1 and MIC1, found in areas associated with familial prostate cancer, as well as TLR4, MIC1, PON1, BRCA2, CHEK2 and OGG, have been identified as contributors to prostate cancer development." (PMID 38971935, 2025). "p‐STAT3, Mcm2, and/or MSR1 were selected out of 10 biomarkers to construct a biomarker index for predicting cancer and high‐grade prostate cancer (HGPCa) in the training cohort based on the stepwise logistic regression analysis; these biomarkers were then validated in the validation cohort." (PMID 32860339, 2020). "However, these mutations appear to have moderate penetrance and are detected in a limited number of cases, therefore, the correlation between hereditary prostate cancer and MSR1 mutations is not currently significant." (PMID 37021836, 2023). "However, only 3 of them have been attributed to pathogenesis and clinical consequence, NM_138715.3 (MSR1): c.520G>T (p.Asp174Tyr) and c.877C>T (p.Arg293Ter) in prostate cancer; and c.760C>G (p.Leu254Val) specifically related to Barrett oesophagus and oesophageal adenocarcinoma." (PMID 36325338, 2022). "To date, germline mutations have been found in three candidate genes for hereditary prostate cancer: ELAC2 at 17p11, RNASEL at 1q25 and MSR1 at 8p22." (PMID 15714208, 2005). "The MSR1 cluster of KLK14 represents the strongest risk factor identified in non-familial breast cancer and an important risk factor for prostate cancer." (PMID 33381518, 2020).